CALR (calreticulin)
Diseases named in the same sentence as CALR in open-access papers (continued):
Sharing a sentence is not in itself a finding about the gene and the disease.
essential thrombocythemia (continued). "One patient with long-standing Calreticulin (CALR)-mutated essential thrombocythemia (ET) later acquired a UBA1 mutation; the UBA1-mutant clone progressively overtook the CALR-mutant clone, extinguishing the ET phenotype as VEXAS features emerged." (PMID 40791602, 2025). "The classic BCR::ABL1-negative MPNs, polycythemia vera (PV), essential thrombocythemia (ET), and primary myelofibrosis (PMF), share an overactive JAK2-signaling as a common characteristic with the key driver genes JAK2, CALR, and MPL." (PMID 38835969, 2024). "Presence of a mutation in JAK2, CALR, and MPL is among the major criteria for the diagnosis of myelofibrosis (MF) or essential thrombocythemia (ET), while presence of JAK2 V617 or exon 12 mutations is among the major criteria for the diagnosis of polycythemia vera (PV)." (PMID 33909614, 2021). "While the BCR-ABL fusion protein is the transforming agent in CML, driver mutations in JAK2, CALR, and MPL genes are variably present and are mostly mutually exclusive in Ph−MPNs, which include essential thrombocythemia (ET), polycythemia vera (PV), and primary myelofibrosis (MF)." (PMID 31963765, 2020). "Somatic mutations in CALR gene have been reported in 60%-88% of patients with essential thrombocythemia (ET) and primary myelofibrosis (PMF) who are negative for JAK2 and MPL mutations." (PMID 30805227, 2019). "CALR Mutation Analysis: No insertions or deletions were detected in exon 9 of the CALR gene, further excluding the possibility of essential thrombocythemia or primary myelofibrosis." (PMID 40969728, 2025). "A subset of essential thrombocythemia (ET) cases are negative for disease-defining mutations on JAK2, MPL, and CALR and defined as triple negative (TN)." (PMID 34489506, 2021). "Thirty-eight patients were classified as essential thrombocythemia of which 52.6% showed JAK2 V617F, 18.4% demonstrated CALR type 1, 7.9% denoted CALR type 2 and there was no mutation reported in 21.1%." (PMID 33936230, 2021). "Mutations of JAK2V617F, CALR, and MPL were analyzed in 159 Malaysian patients using allele-specific polymerase chain reaction, including 76 polycythemia vera (PV), 41 essential thrombocythemia (ET), and 42 primary myelofibrosis (PMF) mutations, and the demographics of the patients were retrieved." (PMID 34300032, 2021). "Calreticulin gene (CALR) mutations frequently occur in Philadelphia chromosome (Ph)-negative myeloproliferative neoplasms (MPNs), including essential thrombocythemia (ET), primary myelofibrosis (PMF), and polycythemia vera (PV)." (PMID 32718354, 2020). "Calreticulin (CALR) exon 9 frameshift mutations, commonly detected in essential thrombocythemia (ET) and primary myelofibrosis patients, activate signal transducer and activator of transcription (STAT) proteins in the presence of Myeloproliferative Leukemia Virus (MPL) and induce ET in vivo." (PMID 30926777, 2019). "CALR mutations were described recently in Janus kinase 2 gene (JAK2)-negative or MPL-negative primary myelofibrosis (PMF) and essential thrombocythemia (ET) patients." (PMID 26377485, 2016). "Indeed, this group of diseases, which include polycythemia vera (PV), essential thrombocythemia (ET), and myelofibrosis (MF), is characterized by the uncontrolled clonal expansion of multipotent bone marrow progenitors driven by acquired mutations in the JAK2, CALR, and MPL genes." (PMID 38338802, 2024). "Calreticulin (CALR) 52 bp deletion and CALR 5 bp insertion have been identified in essential thrombocythemia (ET) and primary myelofibrosis (PMF)." (PMID 39337361, 2024). "Essential thrombocythaemia (ET) is a clonal MPN characterized by excess production of platelets and mature hyperlobulated megakaryocytes, with the presence of mutations in JAK2, CALR, or MPL and the absence of BCR-ABL." (PMID 34778087, 2021).
essential thrombocythemia (continued). "Essential thrombocythaemia (ET) is a rare myeloproliferative neoplasm characterised by elevated platelet counts, megakaryocyte hyperplasia and enlargement, and one of the following: JAK2, CALR or MPL mutations, a clonal marker, or lack of evidence for reactive thrombocytosis." (PMID 33123978, 2021). "rs9376092 has a stronger effect in JAK2V617F-negative cases with CALR and/or MPL mutations (Breslow–Day P=4.5 × 10−7), whereas in JAK2V617F-positive cases rs9376092 associates with essential thrombocythemia (ET) rather than polycythemia vera (allelic χ2P=7.3 × 10−7)." (PMID 25849990, 2015). "Essential thrombocythemia (ET) is one of the classical Philadelphia-negative myeloproliferative neoplasms with different mutations that can be associated with it, like Janus kinase 2 (JAK2), myeloproliferative leukemia protein (MPL), and Calreticulin (CALR) (types 1 and 2)." (PMID 36788855, 2023).
myelofibrosis (73 papers, 2014 to 2026). A partial or complete replacement of the bone marrow stroma by fibrous tissue. "MPL gene mutation was present in only myelofibrosis patients, and CALR gene mutation was present in one of the three cases of leukemic transformation." (PMID 40572650, 2025). "The role of CALR mutations in the development of myelofibrosis is complex as the same mutation can be seen in other MPNs." (PMID 38339265, 2024). "Frameshift mutations in CALR exon 9, in a separate study, were associated with a median overall survival of 131 months in patients with primary myelofibrosis." (PMID 37760623, 2023). "CALR mutations were detected in three of 255 of patients with ≥ grade 2 myelofibrosis, in which, two patients were defined as MDS-f subtype according to WHO 2022 classification." (PMID 37546714, 2023). "In 30-40% of the MPN subgroups essential thrombocythemia (ET) and myelofibrosis (MF), somatic mutations in the calreticulin gene (CALR) are drivers of the disease resulting in constitutive activation of the thrombopoietin receptor (MPL)." (PMID 37223675, 2023). "CALR mutations in myelofibrosis vary in reported frequency (25–53%) but are more common than in patients with PV (not reported) or ET (25–27%)." (PMID 37760623, 2023). "Whereas CALR del52 is a common mutation in MPN patients, ASXL1 mutations arising in myelofibrosis reduce the survival of CALR del52 patients." (PMID 37409695, 2023). "Myelofibrosis patients frequently carry driver mutations in either JAK2 or Calreticulin (CALR) and have limited therapeutic options." (PMID 37828014, 2023). "CALR is recurrently mutated in myelofibrosis, creating a surface‐exposed neoepitope that activates the thrombopoietin receptor." (PMID 35156745, 2022). "Depending on the MPN subtype, patients with ET and type 1-like CALR mutation have a higher risk of myelofibrosis transformation than those with type 2-like mutation." (PMID 36359414, 2022). "Calreticulin (CALR) is recurrently mutated in myelofibrosis via a frameshift that removes an endoplasmic reticulum retention signal, creating a neoepitope potentially targetable by immunotherapeutic approaches." (PMID 35156745, 2022). "The type 1 CALR mutation shows a significantly higher risk of transformation to myelofibrosis in ET, and patients with both CALR types show a higher platelet count, lower hemoglobin and leukocyte values in comparison to JAK2-positive ET." (PMID 34298741, 2021). "This prolonged time may certainly reflect a more indolent nature of CALR-mutated myelofibrosis, or perhaps an initial reluctance to use ruxolitinib in JAK2-negative patients." (PMID 39831987, 2025). "The mutations described in the following sub-sections commonly co-exist with JAK2, MPL, and CALR mutations in patients with myelofibrosis and, while they fall within broad categories (such as proteins affecting splicing and epigenetic regulation), each has its own unique mechanism." (PMID 37760623, 2023). "While true, MPL and CALR mutations predominantly drive ET and myelofibrosis likely due to selective expression of MPL in hematopoietic stem cells (HSCs), multipotent progenitors, common myeloid progenitors (CMPs), megakaryocyte erythroid progenitor cells (MEPs), and megakaryocyte precursor cells." (PMID 35082276, 2022). "Diagnosis of PMF requires demonstration of myeloproliferative mutational markers such as JAK2 or CALR mutation and evaluation of potential causes of secondary myelofibrosis, including infection, autoimmune diseases, chronic inflammatory disorders, malignancies, and toxic agents." (PMID 34749829, 2021). "Calreticulin (CALR) mutation type 1 frequencies in ET are estimated between 7% and 11% and ET patients carrying CALR type 1 mutation are associated with lower risk of thrombosis but higher risk of myelofibrosis transformation compared to ET patients with JAK2 mutation." (PMID 34040959, 2021).
myelofibrosis (continued). "A combination of gene polymorphisms, JAK2, Calreticulin, and MPL driver mutations, and clinical parameters can predict the prognosis and clinical course (overt myelofibrosis or conversion to acute leukemia, thrombosis, and significant bleeding)." (PMID 40572650, 2025). "A separate prognostic scoring system, Myelofibrosis Secondary to PV and ET-Prognostic Model (MYSEC-PM), was established for SMF, in which only the CALR unmutated genotype was considered a high-risk factor." (PMID 38339265, 2024). "Conversely, the Myelofibrosis Transplant Scoring System (MTSS), established to aid in selecting patients for HSCT, considers only the non-CALR/MPL driver mutation genotype and ASXL1 mutation as risk factors." (PMID 38339265, 2024). "The xenotransplant mouse model of these engineered HSC expressing mutant calreticulin developed splenomegaly and myelofibrosis." (PMID 38339265, 2024). "Here, the authors profiled drug responses and proteomics ex vivo and identify molecularly-guided treatment strategies, including HDAC and BET inhibitors for CALR mutant myelofibrosis patients." (PMID 37828014, 2023). "The primary driver mutations in myelofibrosis are well-established and mainly include JAK2, CALR, and MPL mutations." (PMID 37760623, 2023). "It seems that both CALR and JAK2 mutations have a similar risk of transformation to post-ET myelofibrosis." (PMID 37745842, 2023). "We describe transplacental transmission of a CALR-mutant clone between a pair of monozygotic twins, which resulted in the development of overt myelofibrosis after a period of almost four decades." (PMID 35637336, 2022). "Recently, the discovery of mutations in the calreticulin (CALR) genes has closed a gap in the knowledge of the physiopathogenesis of these disorders, particularly for ET and myelofibrosis." (PMID 27134742, 2016). "Along with molecular abnormalities (mutations in JAK2, Calreticulin (CALR) and MPL genes), chronic inflammation is the major hallmark of Myelofibrosis (MF)." (PMID 27304059, 2016). "In this report, we describe a patient with CALR-positive post-ET myelofibrosis treated with intermittent Hu (20 mg/Kg, given as a single dose, thrice weekly), achieving effective disease control, including regression of bone marrow fibrosis from grade 3 to grade 1." (PMID 41464542, 2025). "Additionally, a case has been reported with primary myelofibrosis and triple mutations in JAK2, CALR, and MPL." (PMID 41439212, 2025). "This raises the question of whether prolonged ATP deficiency in the bone marrow predisposes individuals to driver mutations in JAK2, CALR, and MPL, thereby contributing to the development of myelofibrosis." (PMID 41179685, 2025). "Moreover, Dr. Boasman reported that the combination of a Jak inhibitor (ruxolitinib) and an anti-CD47 antibody increased the expression of calreticulin, signaling a much stronger prophagocytic message in cells derived from primary myelofibrosis patients." (PMID 38464520, 2024). "Triple-negative myelofibrosis (TN MF) is diagnosed in the absence of JAK2, MPL, and CALR mutations while otherwise meeting morphologic and laboratory criteria for myelofibrosis." (PMID 37760623, 2023). "4D7 selectively bound to cells co‐expressing mutant CALR and thrombopoietin receptor (TpoR) and blocked JAK‐STAT signalling, TPO‐independent proliferation and megakaryocyte differentiation of mutant CALR myelofibrosis progenitors by disrupting the binding of CALR dimers to TpoR." (PMID 35156745, 2022). "Similarly, we identified the recurrent MH-based CALR deletion in isolated HSPCs and mature cells from two different Myelofibrosis (MF) cases." (PMID 33911081, 2021). "Myelofibrosis (MF) is a clonal disorder of hemopoietic stem/progenitor cells (HSPCs) with high prevalence in elderly patients and mutations in three driver genes (JAK2, MPL, or CALR)." (PMID 33522952, 2021).
myelofibrosis (continued). "In that study, positive rates of CALR mutation were 71%, 56%, and 86% in ET, PMF, and post-ET myelofibrosis patients, respectively, and CALR mutations were associated with higher platelet counts, lower hemoglobin levels, and more extensive fibrosis progression." (PMID 27486987, 2016). "Myelofibrosis (MF) is a clonal neoplasia of the hemopoietic stem/progenitor cells associated with genetic mutations in the Janus kinase 2 (JAK2), myeloproliferative leukemia virus oncogene (MPL), and calreticulin (CALR) genes." (PMID 27672242, 2016). "CALR mutations have been recently identified in a significant proportion of patients with thrombocythemia and myelofibrosis without JAK2 and MPL mutations." (PMID 25068507, 2014). "A four‐tiered Myelofibrosis Secondary to PV and ET‐Prognostic Model (MYSEC‐PM) was specifically developed for secondary SMF, including older age, hemoglobin < 11 g/dL, circulating blasts ≥ 3%, platelet count < 150 ×109/L, constitutional symptoms, and CALR mutational status as variables." (PMID 40062529, 2025). "It has been confirmed that mutations in three key genes, Janus kinase 2 (JAK2), calreticulin (CALR), and myeloproliferative leukemia oncogene (MPL), can increase the activity of blood-producing cells, make them grow more actively, and are associated with the development of myelofibrosis." (PMID 38339265, 2024). "In addition, the MPL mutations are identified in 10% of JAK2V617F negative, CALR negative myelofibrosis." (PMID 27167495, 2016). "As previously noted, JAK2/CALR/MPL/TN mutational status did not appear to impact overall or leukemia-free survival in our current ET patient cohort while MPL mutation was associated with a significantly higher rate of progression to myelofibrosis, as per previous reports." (PMID 38238303, 2024). "Although myelofibrosis is characterized by mutations of JAK2 and calreticulin (CALR), these mutations are not useful to monitor response to therapy." (PMID 27167495, 2016). "The pathogenesis of primary myelofibrosis is not determined solely by alterations in JAK2, CALR, and MPL and likely involves a much broader landscape of somatic mutations, which themselves affect both clinical features of disease and overall survival in various capacities." (PMID 37760623, 2023).
primary myelofibrosis (72 papers, 2014 to 2026). Myelofibrosis with myeloid metaplasia is a myeloproliferative disease with annual incidence of approximately 1 case per 100,000 individuals and age at diagnosis around 60 (an increased prevalence is noted in Ashkenazi Jews). "Somatic mutations in calreticulin (CALR) are present in 25–30% of patients with essential thrombocytosis (ET) and primary myelofibrosis (PMF)." (PMID 35237453, 2022). "Of note, thrombocythemia or primary myelofibrosis patients carry a somatic mutation of the calreticulin gene determining defective interactions between mutant calreticulin, ERp57, and STIM1." (PMID 34685498, 2021). "In contrast to JAK2 mutations being mainly associated with polycythaemia vera, CALR mutations are only associated with primary myelofibrosis (PMF) and essential thrombocythaemia (ET)." (PMID 26202929, 2016). "Gene mutations in epigenetic regulators (ASXL1, TET2, DNMT3A and EZH2) and RNA splicing (U2AF1 and SRSF2) were considered as the additional subclonal mutations and cooperated with the MPN driver mutation (JAK2, MPL or CALR) to play a key role in the pathogenesis of primary myelofibrosis." (PMID 35740649, 2022). "The patient has no JAK2 (Janus kinase 2, V617 F), MPL (thrombopoietin receptor, W515 K/L) and CALR (calreticulin, exon 9 indel) mutation which are identified in approximately 90% of patients to help with the diagnosis and the prognostic stratification of Primary myelofibrosis (PMF) patients." (PMID 32772769, 2020). "Primary myelofibrosis (PMF) is a clonal blood disorder characterized by mutually exclusive driver mutations in JAK2, CALR, or MPL genes." (PMID 40319310, 2025). "Recently, calreticulin (CALR) mutations were discovered in ~30% JAK2/MPL-unmutated ET and primary myelofibrosis." (PMID 28415571, 2017). "The frequency of CALR mutations was 20.3% in 123 MPN patients; 31.1% in ET (n=74), 25% in primary myelofibrosis (n=4) and 2.2% in polycythemia vera (n=45)." (PMID 27486987, 2016). "We investigated the response to IFN in a cohort of 21 CALR mutated MPN patients including ET, prefibrotic primary myelofibrosis (pre-PMF), and primary myelofibrosis (PMF) with a median follow-up of 31 months." (PMID 27764253, 2016). "Somatic frameshift mutations in exon 9 of calreticulin (CALR) gene are recognized as disease drivers in primary myelofibrosis (PMF), one of the three classical Philadelphia-negative myeloproliferative neoplasms (MPNs)." (PMID 37841434, 2023). "The recent discovery of CALR mutations in essential thrombocythemia (ET) and primary myelofibrosis (PMF) patients without JAK2/MPL mutations has emerged as a relevant finding for the molecular diagnosis of these myeloproliferative neoplasms (MPN)." (PMID 25068507, 2014). "According to what has been proposed, CALR mutations could be used as a diagnostic tool in the same way JAK2 alterations have improved accuracy of current diagnosis of essential thrombocythemia and primary myelofibrosis." (PMID 25068507, 2014). "Additionally, hiPSCs derived from patients with the calreticulin (CALR) gene mutation, which is usually found in ET and primary myelofibrosis patients, could reflect disease phenotypes by representing megakaryopoiesis and prominent colony-forming unit megakaryocytes (CFU-MK)." (PMID 34831472, 2021). "However, the patient did not have typical symptoms of primary myelofibrosis (PMF; such as splenomegaly, tear-drop erythrocytes), and previous genetic testing results did not identify PMF-related gene mutations such as JAK2, CALR, MPL." (PMID 40740952, 2025).